LCN2 (lipocalin 2)
Diseases named in the same sentence as LCN2 in open-access papers (continued):
Sharing a sentence is not in itself a finding about the gene and the disease.
Cerebral ischemia (continued). "Astrocytic LCN2 induced by cerebral ischemia or KA treatment promotes neuronal death, neuroinflammation, and oxidative stress." (PMID 34685508, 2021). "Previous studies, including ours, have shown that lipocalin-2 (LCN2) is secreted in response to cerebral ischemia to promote reperfusion injury." (PMID 32872405, 2020). "The current study provided further evidence for the deleterious effect of LCN2 and also suggested effecting astrocyte polarization as a possible mechanism of LCN2 in the acute phase of cerebral ischemia." (PMID 31426811, 2019). "Plasma levels of LCN2 significantly increased as early as 6 hrs, and peaked at approximately 2-fold over baseline by 12 to 24 hrs after cerebral ischemia." (PMID 31269059, 2019). "First, we found that LCN2 levels in plasma significantly increased as early as 6 hours after cerebral ischemia in a rat middle cerebral artery occlusion model, and the elevation of LCN2 persisted till 3 days after cerebral ischemia." (PMID 31269059, 2019). "Firstly, we focused solely on the protein LCN2 and its detrimental role in brain ischemia via the regulation of astrocytes." (PMID 31426811, 2019). "Immunofluorescence staining and Western blot analysis revealed a significant increase in brain LCN2 protein levels after cerebral ischemia." (PMID 29867513, 2018). "Our results showed that EGB significantly inhibited cerebral ischemia development by downregulating the LCN2-activated JAK2/STAT3 signaling pathway and inhibiting astrocyte proliferation." (PMID 29867513, 2018). "Recently, studies have demonstrated that LCN2 is related to a number of CNS injury conditions, such as cerebral ischemia, excitotoxic injury, stab wound, medial forebrain bundle transection, and lipopolysaccharide (LPS)-induced neuroinflammation." (PMID 29867513, 2018). "We found that LCN2 is released from fMLP-stimulated neutrophils in vitro and into the serum after cerebral ischemia." (PMID 25890235, 2015). "We then examined the level of LCN2 in the sera of wild type and Prkcd−/− mice after global cerebral ischemia." (PMID 25890235, 2015). "Here we found reduced release of LCN2 in Prkcd−/− mice following cerebral ischemia, indicating an important role for PKCδ in LCN2 secretion." (PMID 25890235, 2015). "In a variety of CNS injuries (e.g., cerebral ischemia, cerebral hemorrhage, traumatic brain injury, etc.), reactive astrocytes characteristically express LCN2, which can therefore be used as a marker of reactive astrocytes for assessing the extent and prognosis of CNS injury." (PMID 40182140, 2025). "After cerebral ischemia-reperfusion, LCN2 expression is up-regulated." (PMID 40182140, 2025). "Further, by clarifying the specific pathway of LCN2 in cerebral ischemia/reperfusion injury, we can help to develop more targeted therapeutic drugs with fewer side effects and optimize the clinical therapeutic regimen to improve the quality of patients’ survival and prognosis." (PMID 40182140, 2025). "This study reviews the recent research progress of LCN2 in cerebral ischemia-reperfusion injury, revealing that LCN2 is involved in the functional regulation of astrocytes through multiple mechanisms, which in turn affects the injury and repair process of brain tissue." (PMID 40182140, 2025). "Another study has shown that Lcn2 may exert damaging effects after cerebral ischemia by inducing classical activation of astrocytes." (PMID 37672148, 2024). "In a previous study, we showed that LCN2 induces astrocyte activation and exacerbates inflammatory injury in cerebral ischemia, which might function through pro-inflammatory cytokines." (PMID 37353794, 2023). "Studies in Lcn2 knockout mice have shown that neurodegenerative phenotypes, including gliosis in diabetic neuropathy and encephalopathy, intracerebral hemorrhage, cerebral ischemia, spinal cord injury, and optic neuritis, are attenuated in Lcn2 knockouts." (PMID 34136483, 2021).
Cerebral ischemia (continued). "Nitric oxide, produced by iNOS, is known to cause neuronal damage and apoptotic cell death after KA administration, and LCN2 has been shown to produce a damaging effect after cerebral ischemia by inducing high iNOS expression in astrocytes both in vivo and in vitro." (PMID 33445746, 2021). "Moreover, several reports have shown that LCN2 contributes to neuronal cell death in animal brain-injury models, such as LPS-induced neuroinflammation, encephalomyelitis, and cerebral ischemia." (PMID 33445746, 2021). "Moreover, other research data demonstrated the significant role of Lcn2 as stimulator of chemokine release and neuronal cell death in brain ischemia and several other pathological conditions." (PMID 33105802, 2020). "Since LCN2 levels in the blood were significantly elevated in the acute and subacute stage of cerebral ischemia, we asked whether and how LCN2 would affect endothelium, including endothelial proliferation and viability, adhesion, and permeability." (PMID 31269059, 2019). "LCN2 was observed to increase in the cerebral ischemia group compared to the sham group (p < 0.05)." (PMID 29867513, 2018). "In addition, several clinical trials support the experimental laboratory findings that LCN2 is a crucial component of neuroinflammation that mediates brain injury in cerebral ischemia and other pathological conditions." (PMID 29867513, 2018). "Finally, EGB markedly downregulated LCN2 expression in the cerebral ischemia group compared to the sham group (p < 0.01)." (PMID 29867513, 2018). "An EGB injection into the duodenum reduced cerebral ischemia-induced LCN2 levels." (PMID 29867513, 2018). "STAT3 activation has been associated with increased neuroinflammation in cerebral ischemia, of which found that the JAK2-STAT3 pathway was involved in the LCN2 induction of CXCL10 secretion and possibly other phenotypic changes associated with reactive astrogliosis." (PMID 29867513, 2018). "LCN2 release from neutrophils after cerebral ischemia was reduced in PKCδ null mice." (PMID 25890235, 2015). "Thus, the present study aimed to investigate whether LCN2 is involved in astrocyte pyroptosis and whether it is associated with NLRP3 inflammasome activation post-cerebral ischemia/reperfusion injury." (PMID 37353794, 2023). "However, recent studies showed that endothelial cells also can express 24p3R29 and LCN2 may help to maintain BBB integrity in brain ischemia." (PMID 31568658, 2019). "In rodents, lipocalin-2 (LCN2) – the analogous form of NGAL – has been shown to be expressed in response to peripheral inflammation, focal brain ischemia and spinal cord injury." (PMID 34039300, 2021). "The effects of EGB on astrocyte activation, LCN2, p-STAT3, and p-JAK2 expression in the ipsilateral peri-infarct cortical area (-1.7 to -1.9 mm from the bregma) following cerebral ischemia were captured with a laser confocal microscope (Olympus FV1200, Japan)." (PMID 29867513, 2018). "LCN2 induction after BCCAO was greatly reduced in Prkcd−/− mice, indicating a role of PKCδ in mediating LCN2 release after cerebral ischemia." (PMID 25890235, 2015). "As demonstrated in the present study, marked astrocyte activation and LCN2 up-regulation were observed throughout the ischemic cortex area after cerebral ischemia, while EGB treatment significantly inhibited the activation of astrocytes and markedly decreased LCN2 expression." (PMID 29867513, 2018). "Mcam and Lcn2 were decreased in AMEC-KO mice, thus both molecules could be at the heart of the mechanism by which AMEC-KO mice have less damage after cerebral ischemia." (PMID 27640364, 2016).
gastric cancer (29 papers, 2009 to 2026). A primary or metastatic malignant neoplasm involving the stomach. "This leads us to suspect that LCN2 upregulation in gastric cancer could also be linked to ER stress." (PMID 39850877, 2024). "To ascertain whether LCN2 is associated with iron accumulation in gastric cancer, we first analyzed the cohort data from TCGA." (PMID 39850877, 2024). "In addition, expression level correlation analysis using immunohistochemistry, western blot and gelatin zymography have demonstrated that LCN2 is positively associated with invasion and poor progression in oesophageal squamous cell carcinoma and gastric cancer specimens." (PMID 40109857, 2025). "In gastric cancer, low levels of LCN2 suppress cell proliferation, migration, invasion and cell cycle by targeting SLPI." (PMID 40313933, 2025). "The results indicated that LCN2 expression in gastric cancer tissues was significantly higher than in normal gastric tissues." (PMID 39850877, 2024). "Subsequently, we conducted Western blot and immunohistochemical staining on clinical specimens, confirming that the protein levels of LCN2 in gastric cancer tissues were elevated compared to adjacent tissues." (PMID 39850877, 2024). "Elevated serum LCN2 levels have been observed in breast, ovarian, colorectal and gastric cancer, serving as efficient biomarker." (PMID 32076707, 2020). "Moreover, the LCN2/MMP9 complex is correlated with worse overall survival in patients with gastric cancer." (PMID 40109857, 2025). "We proposed that upregulation of ER stress and LCN2 may facilitate iron transport to gastric cancer cells, thus accelerating its advancement." (PMID 39850877, 2024). "Furthermore, survival analysis using data from the KMPLOT website indicated a correlation between LCN2 expression levels and patient prognosis in gastric cancer." (PMID 39850877, 2024). "Furthermore, by comparing and analyzing the expression levels of ER stress related indicators and LCN2 in the TCGA cohort, we found that these markers were highly expressed in gastric cancer tissues." (PMID 39850877, 2024). "Immunohistochemistry and WB experiments on clinical samples further confirmed this finding, indicating that ER stress is elevated within gastric cancer tissues and that the expression of LCN2, an iron transporter, is increased during gastric cancer progression." (PMID 39850877, 2024). "However, the function and role of LCN2 in gastric cancer (GC) remain enigmatic and a subject of debate." (PMID 39850877, 2024). "So, we speculate that complement C5/C5aR can regulate iron metabolism in gastric cancer through regulation macrophages polarization and LCN2 expression." (PMID 39850877, 2024). "Given that LCN2 may play a crucial role in gastric cancer iron metabolism, exploring the mechanisms regulating LCN2 could provide a theoretical foundation for developing it as a novel therapeutic target for gastric cancer." (PMID 39850877, 2024). "We have demonstrated that C5a-C5aR pathway could promote macrophage polarization to M2 phenotype, and up-regulate the expression of LCN2 to enhance iron transport from macrophages to gastric cancer cells, thereby accelerating gastric cancer progression." (PMID 39850877, 2024). "Although the role of Lipocalin-2 (LCN2) in cancer development has been focused on recent studies, the molecular mechanisms and clinical relevance of LCN2 in gastric cancer (GC) still remain unclear." (PMID 35705840, 2022). "Therefore, gastric cancer may upregulate LCN2 to meet its iron demands." (PMID 39850877, 2024). "To further investigate whether C5a/C5aR pathway-induced proliferation of gastric cancer cells occurs via LCN2, we treated THP1 cells with C5a and C5a+ ZINC00640089 (an LCN2-specific inhibitor)." (PMID 39850877, 2024). "However, the effect of LCN2 on iron metabolism in gastric cancer has not been investigated to date." (PMID 39850877, 2024).
multiple sclerosis (29 papers, 2013 to 2026). A progressive autoimmune disorder affecting the central nervous system resulting in demyelination. "Previous studies associated LCN2 with inflammation and cellular damage in cerebral inflammatory diseases such as multiple sclerosis and neuropsychiatric lupus." (PMID 32001681, 2020). "LCN2 has now emerged as a potential clinical biomarker for multiple sclerosis, ageing-related cognitive decline and neuropsychiatric lupus." (PMID 36671050, 2023). "In the central nervous system (CNS), LCN-2 is known to play a role in neuroinflammation under neurodegeneration, glioma, brain injury, and multiple sclerosis conditions." (PMID 35795237, 2022). "Contrastingly, a few studies concerning sepsis, stroke, and multiple sclerosis reported that Lcn2 exerts significant neuroprotective functions, by promoting anti-inflammatory responses and glial pro-recovery phenotypes." (PMID 30501637, 2018). "Moreover, elevated quantities of LCN2 protein have been found in plaques within the brains of individuals with multiple sclerosis." (PMID 38673873, 2024). "This study suggests that gut infiltration of Th17 cells and recruitment of neutrophils are associated with the development of gut dysbiosis and intestinal inflammation, and that fecal Lcn-2 level is a sensitive biological indicator for gut dysbiosis in multiple sclerosis." (PMID 36341389, 2022). "LCN2 was also reported to be increased in CSF and plasma from patients with multiple sclerosis." (PMID 24695528, 2014). "However, LCN2 has also been shown to act as an anti-inflammatory mediator in other CNS diseases, such as experimental autoimmune encephalomyelitis (EAE), a model of multiple sclerosis (MS), and LPS-induced stimulation of bone marrow–derived macrophages." (PMID 37240031, 2023).
ovarian carcinoma (29 papers, 2008 to 2026). A malignant neoplasm originating from the surface ovarian epithelium. "Earlier studies have also demonstrated that LCN2 overexpression is associated with proliferation of human ovarian cancer cell lines." (PMID 27602760, 2016). "In ovarian carcinoma, immunoreactive LCN2 is associated with tumor grade and metastasis." (PMID 40109857, 2025). "The expression of CYBRD1, LRP2, TFRC, SLC22A17, HEPH, SLC39A14, and PCBP2 involved in iron import was associated with poor OS of ovarian cancer, whereas the expression of LCN2, CP, SLC46A1, STEAP3, and LTF in this process was associated with improved OS in ovarian cancer." (PMID 38186569, 2023). "The aim of this study was to determine the concentrations of irisin, chemerin, lipocalin-2 and omentin-1 in the serum and peritoneal fluid of patients with ovarian cancer, as well as in the serum of patients with benign ovarian lesions." (PMID 42057825, 2026). "The highest LCN2 level was found in borderline and grade 1 ovarian carcinoma, while the LCN2 level decreased in advanced ovarian carcinoma." (PMID 40109857, 2025). "Using human ovarian cancer cell lines, the study provided evidence on the mechanism of LCN2 signaling ovarian cancer." (PMID 38645429, 2024). "Hao and co-workers found an up-regulated expression of LCN2 in ovarian cancer patients, as well as in different ovarian cancer cell lines compared to normal tissue and cell lines." (PMID 38645429, 2024). "LCN2 promotes tumor progression in ovarian cancer cells by activating the ERK/GSK3β/β-catenin signaling pathway." (PMID 38645429, 2024). "Conversely, 8 genes showed increased expression in ovarian cancer tissues, including LCN2, CP, TFR2, LRP2, MELTF, LTF, SLC11A2, and STEAP3." (PMID 38186569, 2023). "In stark contrast to its pro-oncogenic function, LCN2 is reported to suppress tumorigenesis in pancreatic, colon, and ovarian cancer." (PMID 34062746, 2021). "For instance, TMPO-AS1 is overexpressed in ovarian cancer and promotes cancer progression via increasing LCN2 transcription." (PMID 34330309, 2021). "The significant down-regulation of LCN2 mRNA was detected in ovarian cancer cells treated with estradiol and genistein, whereas the mRNA expression of ACE2 increased in the kidney after a high dose puerarin and apigenin treatment." (PMID 26151867, 2015). "Increased protein levels for Timp1, Lcn2, Igfbp2, Pfn1, and Sparc were observed in ovarian tumor tissues isolated from K-ras/Pten and Pten/Apc ovarian cancer mouse models compared to control tissue lysates." (PMID 19936259, 2009). "Depending on their findings, Yamada and co-workers speculated that LCN2 is involved in the progression of ovarian carcinoma resulting from endometriosis." (PMID 38645429, 2024). "Furthermore, LCN2 has been reported to increase intracellular iron levels in ovarian cancer cells but decrease oxidative stress, suggesting antioxidant capacity and allowing cancer cells to survive in stressful endometriotic cysts." (PMID 38645429, 2024). "Taken together, the data clearly demonstrate a positive correlation of LCN2 with tumor progression and targeting LCN2 or its signaling pathways could be a therapeutic strategy for targeting ovarian cancer." (PMID 38645429, 2024). "Furthermore, the under-expression of LCN2 is reported to correlate inversely with the severity of ovarian cancer and progression of the EMT as evidenced by decreased E-cadherin and increased vimentin expression." (PMID 34062746, 2021). "In addition, the under-expression of LCN2 was correlated inversely with the severity of ovarian cancer, and in vitro study showed marked enhanced EMT and cellular spread after epidermal growth factor induced inhibition of LCN2 expression." (PMID 34062746, 2021). "We further examined whether Timp1 and Lcn2 were enriched in fluid extracted from late stage ovarian tumors and in peritoneal ascites given the proximity of these fluids to ovarian cancer cells and the secreted nature of the proteins." (PMID 19936259, 2009).
ovarian carcinoma (continued). "In addition, LCN2 is suppressed by EGF in ovarian cancer cell lines undergoing EMT." (PMID 40109857, 2025). "Therefore, LCN2 is a potential marker for monitoring the progression of ovarian cancer." (PMID 40109857, 2025). "Interestingly, LCN2 could be a suitable non-invasive biomarker for ovarian cancer as it is elevated not only in tissue, but also in serum and urine of patients." (PMID 38645429, 2024). "In addition, LCN2 over-expression has been observed in carcinoma of the esophagus, breast, and ovary, and is an independent predictor of overall survival of breast and ovarian cancer." (PMID 34062746, 2021). "Clinically, LCN2 is discussed in the context of polycystic ovary syndrome (PCOS) and ovarian cancer." (PMID 37298232, 2023). "In ovarian cancer, TMPO-AS1 increases LCN2 transcription by binding to transcription factor E2F6, thereby promoting cancer progression." (PMID 34330309, 2021). "For instance, lncRNA TMPO-AS1 boosts the transcription activity of LCN2 by binding to the TF E2F6, thereby facilitating the development of ovarian cancer." (PMID 34858481, 2021). "For example, lncRNA TMPO-AS1 hastens the transcriptional activity of LCN2 by binding to the TF E2F6, thereby boosting the development of ovarian cancer." (PMID 34858481, 2021). "In ovarian cancer, KDM4B is induced under hypoxia, and deletion of KDM4B increases H3K9me3 level at target gene promoters such as the LOXL2, LCN2, and PDGFB promoters, thereby inhibiting the invasion, migration and globulization of ovarian cancer cells." (PMID 35186950, 2021). "It was demonstrated lncRNA TMPO-AS1 potentially fosters LCN2 transcriptional activity by binding to TF E2F6, and thus, stimulates the progression of ovarian cancer." (PMID 34858481, 2021). "Moreover, TMPO-AS1 has the potential to enhance LCN2 transcriptional activity by binding to transcription factor E2F6, thus stimulating ovarian cancer progression." (PMID 37592311, 2023). "Interestingly, liver and ovarian cancer cells with EMT phenotype showed reduced LCN2 expression, while cells with epithelial phenotype had a strong expression of LCN2, which was concordant with our results." (PMID 35705840, 2022). "This suggests that TGF-β may regulate DIMP through LCN2, HMOX1, or HIF1A in ovarian cancer." (PMID 38186569, 2023). "Moderate to strong expression of NGAL/lipocalin 2 was observed in epithelial ovarian cancer cell lines SKOV3 and OVCA433 while no expression of NGAL/lipocalin 2 was evident in normal IOSE29 and mesenchyme-like OVHS1, PEO.36 and HEY cell lines." (PMID 19077278, 2008).